STAT3 (signal transducer and activator of transcription 3)
Diseases named in the same sentence as STAT3 in open-access papers (continued):
Sharing a sentence is not in itself a finding about the gene and the disease.
ovarian carcinoma (continued). "In summary, we have successfully prepared a solid lipid nanoparticle system featuring STAT3 decoy ODN for ovarian cancer therapy." (PMID 25923701, 2015). "Our results thus far indicate that STAT3 inhibition can enhance the sensitivity of ovarian cancer cells to gefitinib." (PMID 25928246, 2015). "Combining EGFR blockade with suppression of JAK/STAT3 signaling is more effective in inhibiting ovarian cancer growth than inhibition of either pathway alone." (PMID 25928246, 2015). "Targeting hypoxia-mediated STAT3 activation represents a therapeutic option for ovarian cancer and other solid tumors." (PMID 25594014, 2014). "We next investigated the role of the specific activation of STAT3 Tyr705 in hypoxic ovarian cancer cells using a deletion mutant at Tyr705 (Phusion Site-Directed Mutagenesis method, Thermo Scientific)." (PMID 25594014, 2014). "GSNO treatment abrogated growth factor (HB-EGF) induced signal transduction including phosphorylation of Akt, p42/44 and STAT3, which are known to play critical roles in ovarian cancer growth and progression." (PMID 24887420, 2014). "Signal transducer and activator of transcription 3 has been shown to be constitutively active in ovarian carcinoma cells and in drug-resistant ovarian cancer." (PMID 25180175, 2014). "Many cancer cell lines and primary tumors, including ovarian cancer, are reported to possess constitutively-active STAT3 (pSTAT3) that can lead to cellular transformation and ultimately tumorigenesis." (PMID 25594014, 2014). "Specifically, we demonstrate that increasing S1PR1 expression in HOCCs initiates STAT3 activation, resulting in enhanced ovarian cancer cell survival and proliferation under hypoxic conditions both in vitro and in vivo." (PMID 25594014, 2014). "Hypoxic preconditioning of ovarian cancer cells results in xenograft tumors that display enhanced tumor growth that is at least mediated in part via activation of the STAT3 signaling pathway." (PMID 25594014, 2014). "This resulted in the decreased expression of STAT3 downstream targets such as Mcl-1 and sensitization of paclitaxel-resistant ovarian cancer cell lines to chemotherapy." (PMID 24782986, 2014). "As a novel finding, we observed that GSNO also induced nitrosylation with inverse relationship at tyrosine 705 phosphorylation of STAT3, an established player in chemoresistance and cell proliferation in ovarian cancer and in cancer in general." (PMID 24887420, 2014). "This supports previous observations and suggests that S1PR1-induced expression of STAT3 is part of a positive feedback loop resulting in persistent STAT3 activation in ovarian cancer." (PMID 25594014, 2014). "Analysis of STAT3 expression in human ovarian cancer specimens was examined via western blot and immunohistochemistry." (PMID 25594014, 2014). "In conclusion, we provide strong evidence that TMOC inhibits cell growth and motility, and induces cell cycle arrest and apoptosis of human ovarian cancer cells through repressing STAT3 and c-Src activation." (PMID 25180593, 2014). "In the current study, for the first time, we show increased activation of STAT3 in hypoxic regions of human epithelial ovarian cancer specimens." (PMID 25594014, 2014). "Recent studies have also shown that sustained STAT3 activation is mediated by IL-6 in ovarian carcinoma, cholangiocarcinoma, colon cancer and lung adenocarcinoma." (PMID 25198511, 2014). "Recent studies have shown that the activation of STAT3 plays a pivotal role in the survival, hyper-proliferation, and metastatic progression of ovarian cancer." (PMID 25180593, 2014). "Recently, some research groups have reported that IL-6 contributes to tumor metastasis and EMT in breast cancer and ovarian cancer via the JAK/STAT3 signaling pathway." (PMID 24789104, 2014). "In the current study, we have proved that the specific activation of STAT3 Tyr705 is required for cell proliferation and survival in hypoxic ovarian cancer." (PMID 25594014, 2014).
ovarian carcinoma (continued). "The present study demonstrated that the anticancer effects of CA on epithelial ovarian cancer cells are due to its suppressive effect on STAT3." (PMID 24260055, 2013). "LPA present in the EOC microenvironment was also reported to induce STAT3 phosphorylation and ovarian cancer cell motility through the secretion of IL-6 and IL-8." (PMID 23369187, 2013). "Direct cell-cell interactions between M2 macrophages and epithelial ovarian cancer cells have previously been reported to induce STAT3 activation and a tumorigenic microenvironment in the ascites fluid of advanced epithelial ovarian cancer patients." (PMID 24260055, 2013). "This compound sensitized cisplatin-resistant ovarian carcinoma, leading to therapeutic synergy through STAT3 inhibition." (PMID 23935247, 2013). "In conclusion, inhibition of IGF-IR and targeting of the JAK2/STAT3 signaling pathway can be a target for ovarian cancer therapy." (PMID 23857432, 2013). "In the present study, coculture experiments were performed, which demonstrated that CA suppressed STAT3 activation and BrdU incorporation in epithelial ovarian cancer cells by abrogating macrophage differentiation into the M2 phenotype." (PMID 24260055, 2013). "Our results are in line with previous reports demonstrating that blockade of IL-6 by its selective antibody inhibits STAT3 phosphorylation in ovarian cancer cells." (PMID 23593315, 2013). "The effect of CA on STAT3 activation was examined and it was demonstrated that CA inhibited STAT3 activation at a concentration of at least 30 μM in the epithelial ovarian cancer cells." (PMID 24260055, 2013). "A similar therapeutic strategy has been reported in ovarian cancer, in which the combined use of the STAT3 inhibitor S3I-201 circumvented cisplatin resistance." (PMID 23382914, 2013). "In vitro coculture experiments have demonstrated that STAT3 activation in epithelial ovarian cancer cells was strongly induced by coculturing with M2 macrophages and was only slightly induced by coculturing with M1 macrophages." (PMID 24260055, 2013). "Activated STAT3 imparts cellular resistance to chemotherapy by inhibiting apoptosis in epithelial malignancies, including ovarian cancer." (PMID 23663277, 2013). "Using a novel purification method we demonstrate for the first time that tumor cells isolated from the ascites of recurrent ovarian cancer patients are enriched with EPCAM+++/STAT3+++ tumor cells compared to cells isolated from the ascites of CN patients." (PMID 23056490, 2012). "Taken together, our results clearly indicate that apoptosis induced by DIM was almost completely blocked in the cells overexpressing STAT3, establishing STAT3 as a target of DIM in ovarian cancer cells." (PMID 22280969, 2012). "Our results are in agreement with a previously published study that showed that STAT3 specific inhibitor (AG490) induced apoptosis in ovarian cancer cells." (PMID 22280969, 2012). "In conclusion, our results firmly establish that DIM induces apoptosis in ovarian cancer cells by inhibiting STAT3 signaling." (PMID 22280969, 2012). "Taken together, our results clearly establish that DIM induces apoptosis in ovarian cancer cells in vitro and in vivo by targeting the STAT3 pathway and synergistically enhancing the effects of cisplatin." (PMID 22280969, 2012). "In this context, a recent study has demonstrated that targeting STAT3 with a small molecule inhibitor can suppress ovarian cancer growth and potentiate the effect of cisplatin in a mouse xenograft model." (PMID 23056490, 2012). "IL-6 also activated HIF-1α, which clearly indicates that HIF-1α perhaps is regulated through STAT3 in ovarian cancer cells." (PMID 22280969, 2012). "A recent study has shown unequivocally that siltuximab (a monoclonal anti-IL-6 antibody) significantly reduced ovarian cancer expression of STAT3 downstream proteins such as Mcl-1, Bcl-X(L), and survivin, implying proapoptotic effects." (PMID 22481932, 2012).
ovarian carcinoma (continued). "Our studies showed that DIM-induced apoptosis in various ovarian cancer cells was mediated by substantially suppressing the phosphorylation of STAT3 at Tyr-705 and Ser-727." (PMID 22280969, 2012). "We demonstrated that DIM induces apoptosis in ovarian cancer cells and enhances the effect of cisplatin by inhibiting STAT3 pathway in culture models." (PMID 22280969, 2012). "The STAT3 expression in normal ovarian tissue (n=20), ovarian cancer tissues (n=25) and ovarian cancer cells (SKOV3 cells) was determined by using immunohistochemistry." (PMID 22933956, 2011). "Our results showed the STAT3 expression was significantly increased in human ovarian cancer when compared with that in normal ovary tissues." (PMID 22933956, 2011). "In contrast, primary ovarian cancer tissues and ovarian cancer cells had moderate to high expression of STAT3." (PMID 22933956, 2011). "pSilencer2.1-U6-siRNA-stat can significantly inhibit the STAT3 expression in human ovarian cancer cells resulting in the inhibition of the cancer growth and the increase of apoptosis of cancer cells." (PMID 22933956, 2011). "Stat3 inhibitors, SD-1029 and SD-1008, greatly induce apoptosis in drug resistant ovarian cancer cells by blocking Stat3 nuclear translocation." (PMID 20459702, 2010). "Previously, we also demonstrated that CDDO-Me inhibits Stat3 pathway in ovarian cancer cells by down-regulation of antiapoptotic genetic expression, and resulted in a dramatic induction of apoptosis." (PMID 20459702, 2010). "The threshold activation of STAT3 in some ovarian cancer cell lines depended on the endogenous level of phosphorylated STAT3." (PMID 19088723, 2009). "To investigate that, we analysed the activation status of JAK2/STAT3 in ovarian carcinoma specimens and correlated that to STAT3 activation in two ovarian cancer cell lines directly by EGFR or indirectly through IL-6R activation." (PMID 19088723, 2009). "This warrants exploration into the significance of EGFR-mediated STAT3 activation in the dissemination of ovarian carcinoma." (PMID 19088723, 2009). "We compared the expression and activation status of JAK2 and STAT3 in a range of benign, borderline, and malignant ovarian tumours and normal ovaries, using immunohistochemistry." (PMID 19088723, 2009). "The results suggested that administration of NCX-4040, in combination with cisplatin, inhibited tumor growth by inducing apoptosis through downregulation of EGFR and STAT3 signaling in the cisplatin-resistant ovarian cancer xenograft in mice." (PMID 18302761, 2008). "STAT3 is constitutively activated in a variety of tumor cell types including A2780 cDDP ovarian cancer cells." (PMID 18302761, 2008). "STAT3 induces the chemoresistance of ovarian cancer cells through multiple mechanisms." (PMID 40968783, 2026). "As stated, IL‐6/STAT3 plays a vital role in the development of drug‐resistant ovarian cancer." (PMID 40968783, 2026). "Overall, these findings identify GA-NPs@DCV as an effective personalized nanovaccine that can simultaneously deliver tumor antigens and the Stat3 inhibitor GA to the tumor microenvironment to exert potent antitumor effects, providing a promising immunotherapeutic strategy for ovarian cancer." (PMID 41743162, 2026). "HO-3867, a curcumin analog, used in combination with CDDP against CDDP-resistant human ovarian cancer (A2780R) cell line, has a synergistic efficacy with significant induction of cell cycle arrest, apoptosis, and tumor growth inhibition through STAT3 inhibition." (PMID 39859517, 2025). "Preclinical studies have demonstrated that LLL12B effectively inhibits tumor cell growth, migration, and invasion across various cancer types including TNBC, medulloblastoma, ovarian cancer, etc., highlighting its potential as a novel therapeutic agent for STAT3-driven malignancies." (PMID 40723906, 2025).
ovarian carcinoma (continued). "siRNA molecules targeting STAT3 have demonstrated promising effects, such as reduced expression levels of STAT3-regulated proteins, reduced proliferation, and increased apoptosis in various types of cancer, including ovarian carcinoma." (PMID 41031165, 2025). "The growth of A2780 ovarian cancer cells is attenuated by CDDO-Im via the JAK/STAT3 pathway." (PMID 39926108, 2025). "Wogonin tends to suppress PI3K/Akt/STAT‐3/HIF‐1 signaling pathways against ovarian cancer." (PMID 41164269, 2025). "Exosomes derived from ascites ovarian cancer cell lines cultured in hypoxic conditions have shown enhanced expression of oncogenic proteins such as STAT3 and Fas cell surface death receptor (FAS), which contribute to increased cellular chemoresistance in vitro." (PMID 40757000, 2025). "Cardamonin’s impact on both mTOR and STAT3 pathways emphasizes its role as a potential therapeutic agent that could disrupt TAMs’ support of ovarian cancer, offering a promising avenue for enhancing immunotherapy in this challenging cancer type." (PMID 40330466, 2025). "Targeting STAT3 signaling by CUR-CDDP could interrupt the anti-apoptotic function of ovarian cancer cells, which leads to increased apoptotic cell death." (PMID 39859517, 2025). "In ovarian cancer, curcumin enhances cisplatin efficacy by inhibiting STAT3-mediated cancer stemness, establishing a mechanistic link between direct molecular targeting of STAT3 and downstream suppression of oncogenic programs." (PMID 41020838, 2025). "Additionally, FBP1 binds to STAT3, blocks the binding of STAT3 to STAT3-mediated gene promoters, inhibits glycolysis in ovarian cancer cells, and improves cisplatin resistance in ovarian cancer." (PMID 39905019, 2025). "The blockade of AKT or STAT3 may benefit ovarian cancer patients experiencing copy number losses or reduced expression of PIK3R1." (PMID 40657399, 2025). "Corosolic acid (CA), a natural compound known for its potent inhibitory effect on STAT3 signaling, shows promise as an adjunctive treatment for epithelial ovarian cancer (EOC) by enhancing the effects of chemotherapy and disrupting tumor-promoting interactions." (PMID 40330466, 2025). "Consequently, dual-inhibition of glutamine entry into the tricarboxylic acid cycle (TCA cycle) and STAT3 signaling provide a promising therapeutic strategy for ovarian cancer." (PMID 38245798, 2024). "Thus, our results indicated that LCP1 can promote EMT by activating the JAK2/STAT3 signaling pathway to promote the resistance of ovarian cancer cells to olaparib." (PMID 39588922, 2024). "We characterized that the crosstalk between OSMR and integrins through their interactions with respective ligands like OSM or fibronectin (FN) leads to the activation of STAT3 transcription factor for prolonged period in chemo resistant and highly aggressive ovarian cancer cells." (PMID 38839865, 2024). "Whether PARPi therapy promotes drug resistance by activating STAT3 in ovarian cancer patients has become a question worth exploring." (PMID 37588193, 2024). "Functional investigations indicate ovarian cancer progression via the IL-6/STAT3/S100A9 pathway." (PMID 39720595, 2024). "The enhanced interaction between T372-phosphorylated EZH2 and STAT3 reduced STAT3 phosphorylation, downregulating interleukin 6 receptor expression and inhibiting the cell proliferation and migration of epithelial ovarian cancer cells in vitro and decreasing ovarian xenograft tumor growth in vivo." (PMID 39769907, 2024). "Monitoring PTP4A3 expression levels and STAT3 phosphorylation status in tumor tissues could be implemented to indicate personalized phosphatase inhibitor treatment for ovarian cancer." (PMID 40836974, 2024).
ovarian carcinoma (continued). "It has been shown that siRNA-mediated PARP1 or a drug that inhibits PARP1 could lead to increased STAT3 phosphorylation in ovarian cancer cell lines." (PMID 37588193, 2024). "We found that our anti-OSMR monoclonal antibodies reduced the ovarian cancer cell growth and progression by inhibiting STAT3 activation and subsequent oncogenic signaling operated through STAT3, inhibiting the levels of survival regulators such as BCl2, PCNA, and inducing cell death." (PMID 38839865, 2024). "miR-222-3p from ovarian cancer cell (SKOV3)-derived exosomes when transferred to tumor associated macrophages (TAMs) induced polarization to the immunosuppressive M2 phenotype and involved the SOCS3/STAT3 signaling pathway." (PMID 38796525, 2024). "Previous research also reported that G-CSF may enhance tumor cell migration and impede chemotherapy-induced apoptosis in ovarian cancer cells via the JAK2/STAT3 pathway." (PMID 37298699, 2023). "Taking advantage of the fact that STAT3 is overexpressed or hyperactivated in ovarian cancer cells, inhibiting STAT3 activation can dramatically suppress tumor growth, suggesting that STAT3 signaling is a promising target for ovarian cancer therapy." (PMID 37238935, 2023). "Moreover, STAT3 shRNA decreased the expression of IL-6 in ovarian cancer cells in vitro and the ovarian xenograft tumor model." (PMID 38067351, 2023). "Additionally, it has been reported that, following IL-6 signaling, phosphorylated STAT3 regulates the nuclear translocation of FoxO3a, leading to increased expression of p27kip1 in T cells, similar to the mechanisms we found in ovarian cancer cells." (PMID 37047012, 2023). "It was shown that inhibiting STAT3 signalling could possibly abolish cisplatin resistance in ovarian cancer patients receiving chemotherapy because STAT3 is constantly active in cisplatin-resistant ovarian tumours." (PMID 36768291, 2023). "Based on our findings, we can conclude that butein from Butea monosperma flower isolates inhibits ovarian cancer growth by binding to IL-6 and suppressing its activity, which results in inactivation of STAT3 and nuclear accumulation of FoxO3a and p27kip1, thereby limiting tumor growth." (PMID 37047012, 2023). "Significant evidence has highlighted the importance of aberrantly activated STAT3 signaling in a variety of cancers, including ovarian cancer cell lines and tissue samples, as detected by microarray analysis, real-time reverse transcription-PCR, Western blot, and the luciferase reporter assay." (PMID 37238935, 2023). "Here, we proposed a novel mechanism by which LicA could inhibit ovarian cancer cell malignancy by downregulating STAT3 translation initiation in SKOV3 cells and then lowering STAT3 protein and activation levels." (PMID 37238935, 2023). "Therefore, RAS and STAT3 activation promote ovarian cancer growth, metastasis, and cisplatin resistance." (PMID 36902166, 2023). "miR-503-5p suppression plays a critical role in CD97 expression (a member of the epidermal growth factor (EGF)—seven-transmembrane family, expressed in many cancers) and the related JAK2/STAT3 pathway for enhancing the metastasis of paclitaxel-resistant ovarian cancer cells." (PMID 38139300, 2023). "Indeed, Erastin enhances metastatic ability of ferroptosis-resistant ovarian cancer cells via macrophages M2-like polarization, through STAT3 pathway and IL-8 release." (PMID 37924062, 2023). "Additionally, myeloid-derived suppressor cells have been found to enhance the stemness of epithelial ovarian cancer cells through activation of the CSF2/p-STAT3 signaling pathway." (PMID 37865637, 2023). "Additionally, the production of IL6 by M2 macrophage can induce cancer cellular proliferation via STAT3 activation in ascites patients with advanced ovarian cancer." (PMID 37792745, 2023). "Furthermore, CAFs elicit TGF-β-mediated EMT in ovarian cancer cells via IL-6-regulated JAK2/STAT3 pathway to inhibit cancer cell apoptosis and provide paclitaxel resistance." (PMID 37065872, 2023).